CD44 (CD44 molecule (IN blood group))
Diseases named in the same sentence as CD44 in open-access papers (continued):
Sharing a sentence is not in itself a finding about the gene and the disease.
tumor (continued). "CXCL12γ promotes tumor development in CRPC, whereas many CD133+/CD44+ CSC-like cells are present in CXCL12γ-overexpressing tumors." (PMID 39092186, 2024). "LIFR silencing markedly impaired tumor formation and decreased CSCs frequency in vivo, accompanied by diminished SOX2, CD44 and ALDH1A1 expression in samples." (PMID 39206755, 2024). "A distinct overexpression of CD1c, CD2, CD3, CD4, CD11c, CD14, CD20, CD44, CD56, CD105, CD146, and CD209 was identified in LCa patients compared to healthy controls, correlating positively with tumor presence." (PMID 38902710, 2024). "Tumor samples derived from Sca-1, CD133, CD44, and CD117-positive cells basal cells possessed the self-renewal ability and reconstituted the prostatic ducts." (PMID 39175878, 2024). "After a 28-day period of exposure to monotherapy, PTX-PPI, or CD44 siRNA-PPI, tumours derived from cells isolated from the malignant ascites of patients with advanced ovarian carcinoma continued to grow." (PMID 39125873, 2024). "We observed that tumor secretions significantly impaired the expression of CD25, CD44, and CD107a in T cells, indicating their suppressive effect." (PMID 38164187, 2024). "Studies have demonstrated a strong positive correlation between the expression of mesenchymal markers such as N–Ca, CD44, and VIM and the expression of chemerin produced by GBM tumor cells." (PMID 37692522, 2024). "This approach revealed that, in both tumor models, CD44+ NB cells exhibited markedly higher BMX expression levels as compared with their CD44– counterparts." (PMID 39133652, 2024). "Tumor cell stemness is usually manifested by the upregulation of OCT4, CD133, and CD44, which were identified as key factors in maintaining stem cell properties, such as self-renewal, tumorigenesis, and drug resistance." (PMID 39444619, 2024). "After 20 days of treatment, the percentage of central memory T cells (CD44+CD62L+) among the CD8+ T subset and the CD4+ T subset in the tumor from mice was significantly higher than that of the PBS group, with 17.4% and 31.6%, respectively." (PMID 38938647, 2024). "Meanwhile, co-culture with NK cells upregulated the expression of KI67, a sign of proliferation for tumor malignancy, and stemness markers CD90, CD44, LGR5, and NANOG in CRC cells." (PMID 38543173, 2024). "But CD44+OT-ICD8+T cells produced higher levels of IFN-γ and TNF-α, and slightly reduced tumor volume." (PMID 38279145, 2024). "Other studies have combined CD44- and CD25-targeted NIR-PIT to simultaneously deplete FOXP3+CD25+CD4+ Treg and CD44+ CSCs in several syngeneic tumor models." (PMID 38612911, 2024). "However, the immunoregulatory role of CD44 in the tumor microenvironment remains unclear." (PMID 38590654, 2024). "CD44 and CD133 serve as classic tumor stem surface antigen markers, which are often used in combination to screen tumor stem cells for various cancers." (PMID 38706601, 2024). "The cell surface molecule, CD44, is another protein highly involved in the EMT-induced metastatic process of cancer cells through its interaction with the tumour microenvironment (TME)." (PMID 38816670, 2024). "Mesenchymal-like BCSCs with CD44+/CD24− characteristics are primarily quiescent and placed at the tumor-invasive front, while epithelial-like BCSCs express ALDH1, are proliferative, and are more centrally located." (PMID 39001543, 2024). "We also examined the expression of chemokine receptors involved in tumor trafficking, CXCR3 and CCR5, in CD44+PD-1+ CD8 T cells from TDLNs." (PMID 39763661, 2024). "The tumor-specific effect of ICT can be achieved by active targeting via the receptor-ligand interaction between HA and CD44 plus passive targeting by accumulation around tumors due to the Enhanced Permeability and Retention (EPR) effect." (PMID 39055490, 2024).
tumor (continued). "Increased expression of CD44, CXCR4 and CD74 on group 1 and 2 NK cells, on which numerous signals from fibroblasts, endothelial cells, tumor cells and macrophages converged (COLLAGEN, MIF, LAMININ), facilitated the augmented incoming signaling in NSCLC." (PMID 38956379, 2024). "Within the CD4+ T cell compartment, there were more T effector/memory (TEM; CD44+, CD62L-) and less T regulatory (Treg; FoxP3+) cells in CR705Parp7KO compared with CR705Cas9 tumours." (PMID 39867896, 2024). "Conversely, within tumor regions representing the IMPC component and LNM, we observed an increase in N-cad expression when CD44 expression decreased, resulting in a disparity." (PMID 38903413, 2024). "In addition, the levels of CD44 gene methylation alone, or in a relevant gene methylation panel from tumor or cell free DNA, could be employed as a prognostic marker in ccRCC, where relevant to tumor aggressiveness." (PMID 38790166, 2024). "Similar trends were also observed in the frequencies of CD44+CD62L− memory effector CD8+ T cells in spleen, and CD8+IFN‐γ+ tumor‐reactive T cells in residual tumors." (PMID 38279587, 2024). "We applied quantitative PCR to determine the expression of 14 genes including CXCR2, SAA, COX1 and COX2, PPAR-α, -δ and -γ, Gro-α and -γ, IL8, p21, c-myc, CD44 and CSF1 in tumor and adjacent normal mucosa of 21 CRC patients." (PMID 38891062, 2024). "In a tumor recurrence model, this combination therapy inhibited secondary tumor growth and increased the percentage of memory T cells (CD8+CD44+), indicating the establishment of immune memory." (PMID 39274842, 2024). "Hyaluronic acid is a major ligand for CD44 (frequently over-expressed on the tumor cell surface) and CD168 which are over-expressed in various tumor and inflammation conditions." (PMID 38257005, 2024). "The findings of mouse tumor IHC and IF further supported the finding that the anti-PD1 + TKI + AA group had higher levels of CD11b and CD44 molecules." (PMID 38822322, 2024). "We have further systematically studied the mechanism of tumor targeting and penetration using 2D, 3D, and mouse tumor models generated with WT and CD44−/− tumor cells, and WT and CD44−/− mice." (PMID 38177179, 2024). "The effectiveness of tumor-targeting by our PCL-CP NPs is likely attributed to both EPR and CS/CD44-mediated active targeting." (PMID 38177179, 2024). "Recently, our research group semi-quantitatively scored the immunoexpression of CSC markers, ALDH1 and CD44, in OSCC samples within the invasive tumour front (ITF) and metastatic lymph nodes as a whole." (PMID 38719848, 2024). "Further analysis of the spleen and TDLNs of these vaccinated mice validated a significant ex vivo activation of tumor‐pulsed splenocytes, determined by an increased proportion of IFN‐γ+ and TNF‐α+ CD44+ CD8+ T cells." (PMID 38666427, 2024). "In a study involving GMB tumor cells, it was demonstrated that the KRAS/ERK signaling pathway regulates the overexpression of CD44 in response to radiation by downregulating micro-RNA expression in GBM cells." (PMID 38672650, 2024). "Overall, the results of this study showed higher expression of cells positive for the selected TME biomarkers (FAK+, CD44+, HIF-1α+, and Ki67+) within tumor nests compared to tumor stroma in tumor resection specimens of EC patients after NRCHT+R." (PMID 38727811, 2024). "CD44 positive GC cells and HOXA11 positive GC cells in tumor fraction were significantly increased in the mice injected with NCI-N87-HOXA11 cells and HMrSV5 cells in comparison to those of mice injected with NCI-N87-Vector cells and HMrSV5 cells (P < 0.05)." (PMID 37989866, 2024). "Conversely, blocking the IL-6/STAT3 signaling pathway hinders CD44 expression as well as the acquisition of CSC-like characteristics and aggressive tumor behavior." (PMID 39092186, 2024).
tumor (continued). "Furthermore, CD44(hi) cells could be serially passaged in vivo, indicating their self-renewal capacity, and they formed tumors that recapitulated the heterogeneity of the original patient tumor." (PMID 39247186, 2024). "The abundant proteins classified as ECM proteins and cell membrane proteins in the protein corona formed in tumor TIF were further analyzed and found that the amount of OPN as an ECM component and transmembrane protein CD44 were higher than other proteins." (PMID 38326312, 2024). "The interaction of HA and CD44 promotes EGFR-mediated pathways, consequently leading to tumor cell growth, tumor cell migration, and chemotherapy resistance in breast, prostate, and gastrointestinal cancers." (PMID 39840036, 2024). "This CD44-CAdTrio allowed HER2-CAR T cells to effectively kill CD44v6+ head and neck carcinoma cells, improving tumor control and survival." (PMID 38672650, 2024). "Verteporfin effect inhibited Y/T-TEAD transcriptional activity, cell proliferation and CD44 expression, reduced the pool of tumor-forming CD44+/aldehyde dehydrogenase (ALDH)-high gastric CSCs, and inhibited GC tumor growth in vivo." (PMID 38544822, 2024). "The interaction between CD44 and HA activates different signaling pathways, including MAPK, which can lead to an increase in tumor cell proliferation and migration." (PMID 39194478, 2024). "Triple combination treatment also reduced the CD44+/CD24− subpopulation of cells (BCSC marker) and reduced tumor cells capable of tumor initiation, as shown by limiting dilution assay." (PMID 39737957, 2024). "The continued stemness of tumor cells, which is sustained by the OPN/CD44 autocrine loop, triggers the Akt pathways." (PMID 37692522, 2024). "Immunofluorescence staining of tumor sections indicated a decrease in SOX4 and CD44 expression in tumors of mice treated with IBRD9 compared with untreated tumors." (PMID 37739089, 2024). "We found that most of the receptors that interact with tumor cells are CD44 and ITGA families, which are related to the processes of tumor cell proliferation and invasive movement." (PMID 39716897, 2024). "They demonstrated that blocking CD44 function reduces GSC invasiveness and tumor growth, suggesting its potential as a therapeutic target to limit GBM spread." (PMID 39063221, 2024). "Mounting evidence suggests that CD44 is a CSC marker and critical regulator of cancer stemness, including self‐renewal, tumour initiation and metastasis." (PMID 38722284, 2024). "Exploiting the potential of P-selectin on the surface of megakaryocyte-derived exosomes to bind to CD44, which is highly expressed on the surface of GBM cells, we achieved precise active targeting to tumor cells." (PMID 38762500, 2024). "Cell therapy with rCD8+ T-cells reduced the amount of Axl+, Axl+CD117+, CD117+ EGF+CD44+PD-L1+PD-1+ and CD117+CD44+ cells in the lungs of mice with spontaneously metastatic tumor." (PMID 38664641, 2024). "Blocking CD44 function reduces GSC invasiveness and tumor growth, suggesting its potential as a therapeutic target for limiting GBM spread." (PMID 39063221, 2024). "Furthermore, we established a therapeutic model by administering an anti-PTX3 antibody [WHC-001; a neutralizing antibody that binds to PTX3, preventing its interaction with CD44] to evaluate whether blocking PTX3 in the tumor microenvironment can mitigate stroma-mediated tumor growth." (PMID 38243273, 2024). "CD44 is involved in cell-cell interactions and migration, and also activates MMP-9 which promotes tumor angiogenesis through TGF-β activation." (PMID 39758992, 2024). "During the transportation into liver and tumor from blood, CP1-LVs exhibited different adsorption behaviors of proteins in liver and tumor TIF, especially the adsorption of IgG, OPN, and CD44." (PMID 38326312, 2024).
tumor (continued). "After gating out IL-17-producing CD44+CD45RB− (γδ17) T cells, we clearly detected CD8αβ+ γδ T cells as tumor-infiltrating lymphocytes (TILs), albeit with notably less abundance than CD8− γδ T cells." (PMID 38802512, 2024). "In those patients, a stronger expression of FAK+, CD44+, and ILK+ cells was found in tumor nests between the fiducial markers (former GTV) and beyond (former CTV), even after NRCHT." (PMID 38727811, 2024). "Targeting CD44, for example, can potentially reduce CSC-related tumor progression, relapse, and even metastasis." (PMID 39518076, 2024). "In the context of signal regulation by TEXs in tumor cells, our findings pointed to MIF-(CD74+CD44) as a significantly more potent regulatory signal, playing a pivotal role in driving malignant tumors." (PMID 38683136, 2024). "Genetic parsing of a variety of tumor stem cells has revealed that tumor stem cells contain specific markers, such as CD24, CD44, CD133 and EpCAM, whose importance for the maintenance and activity of tumor stem cells is unclear." (PMID 39744013, 2024). "In breast cancer, one such cell population is characterized by several molecular markers (CD44 positive, NRP1 high, ALDH1 positive, and CD24 low) and is often referred to as the cancer stem-like cell (CSC) population or tumor-initiating cells." (PMID 39420119, 2024). "Immunohistochemical staining of nude mouse subcutaneous tumor model of SOX2, CD44, CHI3L1, and CD24 in vivo shows the same result, and IHC staining of TAM markers CD68 had no obvious change." (PMID 39619148, 2024). "TEMs (CD3+CD8+CD44+CD62L−) play an important role in secreting TNF-α and IFN-γ to eliminate tumor cells." (PMID 38807377, 2024). "On the contrary, CP1-LVs with protein corona formed in tumor TIF exhibited little advantage in uptake in the HUVEC cells with low expression of integrin and CD44, compared with other nanovesicle groups." (PMID 38326312, 2024). "We observed an expression of CD24, CD44, and NANOG, indicating a highly potent capacity to rebuild the tumor mass." (PMID 39408826, 2024). "Significant upregulation in the gene expression level of tumor stem cell markers CD24, CD44, CD133, and EPCAM were also observed in the 3D Mixed organoids compared to both HUH-7 cell line and 3D HUH-7 organoids." (PMID 38773585, 2024). "Several cell adhesion receptors, such as CD44 and PECAM1 (Platelet Endothelial Cell Adhesion Molecule 1), were highly expressed in tumor samples." (PMID 38979413, 2024). "Gal9‐KO in tumor organoids #2 and #3, generated using the CRISPR/Cas9 system, significantly reduced the ALDH+/CD44+ TIC ratio." (PMID 38528665, 2024). "This section will delve into the specific properties of HA concerning the tumor ECM and anticancer therapy, while the interaction with its main receptor CD44 will be explored in Section 4.4." (PMID 39062846, 2024). "A higher expression of the mesenchymal markers CD44 and CD73 was also demonstrated in tumour cells compared to margin and control cells (p < 0.05)." (PMID 39126021, 2024). "Results showed that the mRNA levels of BNIP3, CYCS, RRAGD, CD44, EIF4E, MAP4K1, and LIN28B were higher in tumor samples, whereas the mRNA levels of PPARGC1A and FLT3 were higher in normal samples." (PMID 38468074, 2024). "Immunohistochemistry was performed on formalin-fixed paraffin-embedded (FFPE) tumor tissue samples to assess the expression of CSC markers (CD133, CD44, and L1CAM) and immune checkpoint inhibitor marker (PD-L1)." (PMID 39148690, 2024). "Finally, better elucidation of the mechanisms used by TAMs to facilitate disease progression/metastasis along with thorough characterization of the tumor molecular landscape (i.e. expression of high levels of CD44/visfatin/miR760) could provide alternative targeted therapies for individual patients." (PMID 39044824, 2024). "Some clusters expressed a combination of markers associated with tumor proliferation and invasiveness, such as CD44, S100A4, CD74 and MMP-9 (Tumor 7, 29.1%, n=8; range 0.7-81.5% per PDAC)." (PMID 39575252, 2024).
tumor (continued). "While the role of endothelial CD44 for angiogenesis is well described, a direct influence of TC CD44 on VEGF release and, thus, tumor microvessel formation has so far, to the best of our knowledge, rarely been described." (PMID 37849446, 2024). "CD44 is one of the earliest and most commonly acknowledged CSC markers intimately involved in tumor invasion and metastasis." (PMID 38609981, 2024). "MDSCs and tumor-derived OPN have been shown to abrogate T cell activation and T cell-mediated IFN-γ secretion via interaction with CD44 on T-cells, leading to poor patient survival." (PMID 39062100, 2024). "MMP-13 promotes tumour angiogenesis 16, MMP-7 degrades HB-EGF and E-cadherin in the basement membrane 17, 18, and MMP-14 degrades CD-44 and electron-cadherin in the basement membrane 19, which together play a vital role in tumour invasion." (PMID 38911387, 2024). "Intraperitoneal injections (2 nmol/mouse/every two days) of the bi-specific CD44-EpCAM aptamer in mice bearing ovarian OVCAR8 tumors resulted in increased cancer cell apoptosis and a significant reduction in tumor growth." (PMID 38612911, 2024). "The new knowledge generated is the computed score for CD44, EGFR, E-cadherin, and vimentin, which can be used as indicators to predict tumor aggressiveness by implicating recurrence." (PMID 39050298, 2024). "In vitro experiments showed that compared with 2D GC cell culture, the expression of ONECUT2 protein and stemness-related markers CD44, SOX9, SOX2, and LGR4 simultaneously increased in 3D tumor stem cell spheroid culture." (PMID 38997271, 2024). "The extent of the research gap filled is that we have been able to validate the utility of CD44, EGFR, E-Cadherin, and vimentin as indicators of tumor aggressiveness and recurrence." (PMID 39050298, 2024). "As one of the classical and important ligands of CD44, OPN affects the proliferation and invasion of tumor cells as well as inflammation in normal cells, by regulating related signaling pathways." (PMID 38783892, 2024). "It’s found that IHC signals of BNIP3, CYCS, RRAGD, CD44, EIF4E, and MAP4K1 were consistently high in tumor cells of HCC, compared with normal tissues, implying that these genes were indeed ectopically expressed in HCC." (PMID 38468074, 2024). "In line with this, tumor cells expressing ligands engaging IRs such as BDCA-2, ILT7, TIM3 and CD44 block pDC activation, while this blocking is prevented when IR engagement or signaling is inhibited." (PMID 38504978, 2024). "The co‐expression of any 1 gene from Group A (C19orf33, S100A14, and RHOD; count ≥1) and any 1 gene from Group B (CST6, CD44, TM4SF1, and TACSTD2; count ≥1) in a single tumor cell was defined as a MIC." (PMID 38864342, 2024). "Tumorigenesis and increased tumor volumes were observed in those mice transplanted with CD44-high/CD166+ cells also showing high MACC1 and LGR5 levels (vs. CD44-low/CD166+ cells)." (PMID 38339354, 2024). "Firstly, we investigated the enrichment of CSC markers CD133, CD44 and SSEA4 upon Gemcitabine chemotherapy reagent treatment in tumours from three PDAC patients." (PMID 38678032, 2024). "CD44, ETS2, RHOH, and TRIB1 also affect the proliferation and invasion ability of tumor cells by regulating the expression of downstream genes." (PMID 39684426, 2024). "The uptake efficiency in both A549 and HeLa cells was reduced after CL or HA preincubation with tumor cells, suggesting the important roles of OPN and CD44 in the tumor cell uptake of nanovesicles in the tumor environment." (PMID 38326312, 2024). "This is the first prospective study of the clinical value of CD44 and CHI3L2 SNV–based biomarkers in PDAC after tumor resection." (PMID 38635586, 2024). "The findings demonstrated that cluster 1 has highly expressed immunosuppressive sites such as BTLA, CD200, CD200R1, CD44, HAVCR2, etc. that promote immunosuppression and tumor formation." (PMID 38347320, 2024).